STAT3 (signal transducer and activator of transcription 3)
Diseases named in the same sentence as STAT3 in open-access papers (continued):
Sharing a sentence is not in itself a finding about the gene and the disease.
Cerebral ischemia (90 papers, 2011 to 2026). Restriction of arterial blood supply to the brain associated with insufficient oxygenation to support the metabolic requirements of the tissue. "To understand the mechanism of upregulation of hepcidin caused by brain ischemia, we further examined the expression of STAT3 and phosphorylated STAT3 (p-STAT3) in the cerebral cortex, hippocampus and corpus striatum." (PMID 21957487, 2011). "However, factors remaining to be determined include the potential for STAT3 activation in mitochondria after cerebral ischemia injury, whether STAT3 is affected by Hcy, and the mechanisms associated with such potential effects in the ischemic brain." (PMID 28761070, 2017). "Early evidence from Li and Zhang revealed that genistein inhibited STAT3 phosphorylation and DNA-binding activity in the rat hippocampus following cerebral ischemia/reperfusion, indicating direct blockade of a major inflammatory transcription factor." (PMID 41433336, 2025). "On the contrary, a recent study has reported that the STAT3/HIF-1α/PTRF axis exacerbates cerebral ischemia/reperfusion (I/R) injury." (PMID 40653468, 2025). "For instance, STAT3 has been shown to mediate endogenous IL-6 to prevent apoptosis of neurons in the acute phase of cerebral ischemia." (PMID 40313716, 2025). "After cerebral ischemia, STAT3 can be activated, and then promote the transcriptional regulation of several key molecules inducing brain injury." (PMID 40715012, 2025). "Dex pretreatment alleviated cerebral ischemia/reperfusion injury by inhibiting neuroinflammation through the JAK2/STAT3 pathway." (PMID 38364236, 2024). "PIAS3 regulates the transcription activity of signal transducer and activator of transcription 3 (STAT3), which has been implicated in cerebral ischemia." (PMID 38456949, 2024). "The JAK2/STAT3 signalling pathway is critically involved in regulating the formation of various tumours and cerebral ischemia and Alzheimer's Disease (AD) treatment." (PMID 39392081, 2024). "Specifically, circFOXP1 was found to regulate apoptotic signaling through binding to and modulating STAT3 activity in models of cerebral ischemia." (PMID 37869777, 2024). "Neuronal STAT3/HIF-1α/PTRF axis-mediated bioenergetics can exacerbate cerebral ischemia–reperfusion injury via PLA2G4A55." (PMID 38360841, 2024). "Some studies have shown that activation of the STAT3 pathway after cerebral ischemia can change the microglial phenotype from pro-inflammatory to anti-inflammatory, partially improving brain injury." (PMID 38384585, 2024). "As a member of the STAT protein family of transcription factors, STAT3 is a well‐established regulator of inflammatory gene expression and is rapidly activated during the acute phase of cerebral ischemia." (PMID 37869777, 2024). "Previous studies suggest that: the inhibition of IL-6 leads to a decreased STAT3 phosphorylation, which exacerbates cerebral ischemia, and the activation of STAT3 increases ischemic myocardial survival." (PMID 38022526, 2023). "According to studies, the post-ischemic inflammatory response is mediated by the JAK2/STAT3 signaling pathway, which can be activated after cerebral ischemia." (PMID 37886007, 2023). "After 3 h of reperfusion, p‐STAT3 was detected in the nuclei and increased in the nuclear 24 h after reperfusion, indicating that p‐STAT3 translocation occurred soon after cerebral ischemia as an early step of activated signal transduction." (PMID 36419252, 2023). "It’s worth noting that the JAK2/STAT3 signaling pathway likely has a biphasic in regulating cerebral ischemia." (PMID 37361996, 2023). "During cerebral ischemia, STAT3 is expressed in activated microglia, astrocytes, and endothelial cells, which are closely associated with inflammation." (PMID 37361996, 2023). "At present, experiments have demonstrated that curcumin can improve neuronal survival rate by activating JAK2/STAT3 signals, as well as reduce cerebral ischemia-reperfusion injury." (PMID 36598916, 2023).
Cerebral ischemia (continued). "In contrast, some studies have suggested that the phosphorylation of STAT3 contributes to neuronal apoptotic death after cerebral ischemia." (PMID 36419252, 2023). "Increasing studies have demonstrated that the JAK2/STAT3 signaling pathway is activated immediately after cerebral ischemia, plays a pivotal role in microglia activation, and acts as a potential therapeutic hotspot in neuroinflammation and neuronal apoptosis." (PMID 37143406, 2023). "Previous research has shown that pharmacological inhibition of the JAK2/STAT3 pathway can reduce inflammatory response after cerebral ischemia and exert neuroprotective effects." (PMID 38137105, 2023). "Previous work demonstrated the involvement of Stat3 in long-term functional recovery after brain ischemia by inducing angiogenesis, extracellular matrix remodeling, and neuroplasticity." (PMID 37691115, 2023). "Signal Transducer and Activator of Transcription 3 (STAT3) plays a role in a wide range of biological processes in brain, including protection from cerebral ischemia." (PMID 36293020, 2022). "The objective of this study was to determine the role of STAT3 in cerebrovascular endothelial cell (EC) survival and function, and its role in tissue outcome after cerebral ischemia." (PMID 36293020, 2022). "Previous studies have suggested that JAK2/STAT3 is closely related to cerebral ischemia and can be activated during the early stages of cerebral infarction." (PMID 36446389, 2022). "By contrast, cerebral ischemia induces the A2 phenotype through the signal transducer and activator of the transcription 3 (STAT3) pathway, which exerts neuroprotective effects by releasing neurotrophic factors." (PMID 35966781, 2022). "Aberrant activation of STAT3 after cerebral ischemia leads to neuroinflammatory processes and promotes transcription and expression of genes involved in proinflammatory mediators including inflammatory enzymes." (PMID 36698776, 2022). "We conclude that STAT3 is vital to maintaining cerebrovascular integrity, playing a role in EC survival and function, and protection against cerebral ischemia." (PMID 36293020, 2022). "Consistently, hMSC reduced microglial STAT3 gene expression and activation of Y705 phosphorylated STAT3 following transplantation in an ouabain-induced brain ischemia rat model, which resulted in decreased microglia activation." (PMID 36742051, 2022). "A member of its family, the JAK2/STAT3 signal pathway, is involved in neuronal death and nervous reorganization in ischemic encephalopathy." (PMID 35468096, 2022). "In our study, rats with cerebral ischemia exhibited increased IL-6 expression and Jak2 downstream Stat3 protein phosphorylation in the injured cortical tissues, livers, and gastrocnemius muscles." (PMID 34943061, 2021). "Many lines of evidence have indicated that JAK2/STAT3 signaling is activated in the early stage of cerebral ischemia and mediates oxidative stress, the inflammatory response, and neuronal apoptosis." (PMID 33790691, 2021). "In summary, our present study suggests that AIM2/STAT3 inhibition in endothelial cells is a promising therapeutic strategy for BBB impairment after cerebral ischemia." (PMID 34156153, 2021). "Recent studies showed that inhibition of Cx43 hemichannels alleviated cerebral ischemia via the toll-like receptor (TLR4) or JAK2/STAT3 pathway." (PMID 32982919, 2020). "After cerebral ischemia reperfusion, the STAT3 signaling pathway is activated and inhibition of the activation of this pathway has a brain protective effect in decreasing neuron death and neurological deficit." (PMID 33133212, 2020). "Previously, it was demonstrated that Jak1 and Stat3 mediated pathway is activated in astrocytes following a transient focal cerebral ischemia (50-min occlusion)." (PMID 31733648, 2019). "Many previous studies are agree with that the activation of the JAK2/STAT3 pathway attenuates brain ischemia/reperfusion injury." (PMID 31827699, 2019).
Cerebral ischemia (continued). "Our results showed that EGB significantly inhibited cerebral ischemia development by downregulating the LCN2-activated JAK2/STAT3 signaling pathway and inhibiting astrocyte proliferation." (PMID 29867513, 2018). "The present study demonstrated that a strong induction of microglial STAT3 occurred in rat hippocampus after cerebral ischemia by immunohistochemistry." (PMID 28923114, 2017). "The potential for crosstalk between ROS production and STAT3 activation in the relevant mechanisms during cerebral ischemia-reperfusion injury was also investigated." (PMID 28761070, 2017). "It has recently been reported that a ROS scavenger inhibits STAT3 activation induced by cerebral ischemia/reperfusion damage in rats, reduces infarct size and improves neurological outcomes." (PMID 21682888, 2011). "It has been reported that STAT3 activation is necessary for improved axonal regeneration in the spinal cord after injury and that the suppression of STAT3 activation induced by brain ischemia in microglia prevents inflammation and brain damage." (PMID 21682888, 2011). "CIGs mitigate neuroinflammation in autoimmune encephalitis and traumatic brain injury by inhibiting the JAK/STAT and NF-κB/STAT3 pathways, while protecting against white matter lesions in rat models of cerebral ischemia through activation of the BDNF/Neuregulin-1 pathway." (PMID 41403435, 2025). "Recent studies have found that glycolysis can increase inflammatory responses to cerebral ischemia by up-regulating the phosphorylation of STAT3, which in turn enhances the infiltration of peripheral blood neutrophils and the expression of inflammatory cytokines." (PMID 39926015, 2025). "It should moreover be noted that the pro-angiogenetic effect of IL-17A may be dependent on the IL-6/STAT3 signaling pathways under EE conditions after cerebral ischemia; this matter should be further explored in the future." (PMID 36873773, 2023). "STAT3 has been proved to have an important relationship with the survival and regeneration of neurons in various central nervous system injury models such as cerebral ischemia injury and spinal cord injury." (PMID 37894835, 2023). "The JAK1/STAT3 pathway is activated after cerebral ischemia." (PMID 38022526, 2023). "Studies have reported the activation of the neuronal JAK/STAT signaling pathway after cerebral ischemia, in which STAT3 plays an important role in neuroprotection by inducing neuroprotective genes such as Bc1-2, with an increasing STAT3 expression in ischemic regions." (PMID 38022526, 2023). "Inhibiting Stat3 phosphorylation within 72 h of cerebral ischemia decreased lesion size." (PMID 36698776, 2022). "We tested the hypothesis that endothelial STAT3 contributes to protection from cerebral ischemia, by preserving cerebrovascular endothelial function and blood–brain barrier (BBB) integrity." (PMID 36293020, 2022). "Similarly, Stat3, which is predominantly expressed by activated microglia and other macrophages 24 to 72 h after cerebral ischemia, is said to promote angiogenesis by regulating the migration and proliferation of CVEs." (PMID 36698776, 2022). "As a gene target of STAT3, survivin is of significance to the neuroprotection of estradiol, as evidenced by the finding that the shRNA of survivin reversed the neuroprotection in the rat models of cerebral ischemia." (PMID 35685607, 2022). "Furthermore, data from a rat model of focal brain ischemia revealed that intracerbroventricular infusion of a pJAK2 inhibitor, an upstream regulator of STAT3 has reduced infarct size, downregulated apoptosis and moderated the severity of neurological damage." (PMID 35015765, 2022). "Besides this, the inhibition of the Jak2/Stat3 pathway that can be activated with excess IL-6 during the acute phase of cerebral ischemia confers neuroprotection in ischemic stroke." (PMID 34943061, 2021).
Cerebral ischemia (continued). "In addition, STAT3 activation has also been shown to preserve NK cell function by increasing IFN-γ release in the splenic NK cells after brain ischemia." (PMID 35185544, 2021). "There are contrary functional options about JAK2/STAT3 activation in cerebral ischemia." (PMID 31827699, 2019). "Based on these results, leptin may regulate mitochondrial respiratory chain enzymatic activities via mitochondria‐targeted STAT3 to reduce ROS production and protect brain tissues from mitochondrial oxidative stress during cerebral ischemia." (PMID 30632310, 2019). "However, there is little research about mitochondrial STAT3 in cerebral ischemia-reperfusion injury." (PMID 31816825, 2019). "Estrogen is protective in a mouse model of brain ischemia due, in part to STAT3 activation." (PMID 31683879, 2019). "STAT3 activation has been associated with increased neuroinflammation in cerebral ischemia, of which found that the JAK2-STAT3 pathway was involved in the LCN2 induction of CXCL10 secretion and possibly other phenotypic changes associated with reactive astrogliosis." (PMID 29867513, 2018). "In addition, it has been demonstrated that neuroinflammatory processes after cerebral ischemia involve aberrantly activated STAT3." (PMID 28923114, 2017). "However, little is known about changes in activation of microglial STAT3 in rat hippocampus after brain ischemia, despite the finding that hippocampus is one of the most vulnerable brain regions to ischemic damages." (PMID 28923114, 2017). "In addition, STAT3 has been observed to be phosphorylated at serine 727 under oxidative stress to enhance the transcription activity of STAT3 in previous cerebral ischemia preconditioning study." (PMID 23573126, 2013). "Therefore, cerebral ischemia-reperfusion induced the activation of STAT3 and NF-κB, including both the independent and dependent pathways of IκB degradation." (PMID 23437066, 2013). "Our findings suggest that postischemic treatment with KRS or KGS attenuates cerebral ischemia-reperfusion injury and neuroinflammation by inhibiting the activation of STAT3 and NF-κB and has the therapeutic potential for the neuroinflammation-related diseases, such as ischemic stroke." (PMID 23437066, 2013). "Furthermore, our findings revealed additional proteins that may serve as biomarkers for cerebral ischemia-reperfusion injury, including STAT3, NME2, VCL, and CCT3." (PMID 39936033, 2025). "Stat3 could also be involved in mechanisms of protection against heart and brain ischemia." (PMID 23825704, 2013). "More importantly, STAT3 is a transcription factor for Manganese superoxide dismutase (Mn-SOD), and it is involved in neuroprotection against cerebral ischemia." (PMID 40653468, 2025). "For instance, resveratrol has a neuroprotective effect against cerebral ischemia/reperfusion injury by up-regulating the expression of p-JAK2, p-STAT3, p-AKT, p-mTOR, and Bcl2, and down-regulating the expression of cleaved caspase-3 and Bax." (PMID 36940077, 2023). "EP was also found to attenuate the abnormal activation of the JAK2/STAT3 signaling pathway after cerebral ischemia, indicating the potential significance of the JAK2/STAT3 pathway in the neuroprotective effects of EP." (PMID 37143406, 2023). "In conclusion, ASIV inhibited the brain infiltration and activation of NK cells during the acute stage of brain ischemia in mice, and these effects of ASIV likely depended on STAT3 inhibition." (PMID 35185544, 2021). "The effects of EGB on astrocyte activation, LCN2, p-STAT3, and p-JAK2 expression in the ipsilateral peri-infarct cortical area (-1.7 to -1.9 mm from the bregma) following cerebral ischemia were captured with a laser confocal microscope (Olympus FV1200, Japan)." (PMID 29867513, 2018). "In the present study, astrocytic p-STAT3 and p-JAK2 were up-regulated after cerebral ischemia in vivo and after OGD in vitro." (PMID 29867513, 2018).
Cerebral ischemia (continued). "Taken together, our findings suggest that Sino exerts potent therapeutic effects in cerebral ischemia by targeting astrocytic DRD2 and suppressing neuroinflammatory injury via the CRYAB/STAT3 pathway." (PMID 27724964, 2016). "In summary, our study demonstrates that Sino possesses potent therapeutic effects in cerebral ischemia and suppresses neuroinflammatory injury via targeting astrocytic DRD2 and the CRYAB/STAT3 pathway." (PMID 27724964, 2016). "This suggests that STAT3 activation after cerebral ischemia is not the only negative effect of neural tissue damage." (PMID 39926015, 2025). "Cerebral ischemia can trigger the phosphorylation of both STAT1 and STAT3." (PMID 37361996, 2023). "Moreover, another three potential drugs, phloretin, cucurbitacin B, and bimosiamose, which are the inhibitors of AQP9, STAT3, and SELL, respectively, have been reported to improve neurologic deficits after rat cerebral ischemia by reducing oxidative stress." (PMID 37180174, 2023). "The role of endothelial STAT3 signaling in cerebral ischemia/reperfusion has not been fully elucidated." (PMID 36293020, 2022). "In addition, double-immunofluorescence staining also demonstrated that astrocytic p-STAT3 and p-JAK2 levels were markedly increased after cerebral ischemia but were diminished by EGB treatment." (PMID 29867513, 2018). "There is no existing evidence that STAT3 is involved in neuronal apoptosis by the regulation of Bcl-2 and Bax expression following cerebral ischemia." (PMID 25092271, 2014). "By inhibiting JAK2/STAT3 signaling pathway, curcumin reduces the expression of HMGB1 in brain tissue after cerebral ischemia and reduces the release of TNF‐α and other inflammatory factors after cerebral ischemia, which significantly reduce the inflammatory response after cerebral ischemia." (PMID 38156383, 2023). "Furthermore, the anti-inflammatory properties of N15 may contribute to its neuroprotective effects on cerebral ischemia, at least in part, by boosting PPAR/dual signaling and suppressing the activation of the NF-κB, STAT3, and ERK1/2 signaling pathways." (PMID 36120593, 2022). "There are several cellular signaling pathways that may represent such “crossroads”, connecting brain ischemia and AD; recent research has indicated candidates such as Notch, signal transducer and activator of transcription 3 (Stat3), or Wnt signaling." (PMID 34575845, 2021).